ARMCX2 (armadillo repeat containing X-linked 2)
Description:
May regulate the dynamics and distribution of mitochondria in neural cells.
Synonyms: ALEX2; KIAA0512; GASP9
Tractability: Antibody: UniProt predicts a signal peptide or a membrane-spanning region. PROTAC: ubiquitination databases record sites on it; its protein half-life has been measured.
Gene: Protein-coding gene on chromosome X (101,655,157 to 101,659,924, reverse strand). Ensembl gene ENSG00000184867.
Subcellular location: Mitochondrion; Mitochondrion outer membrane
Subcellular location (Human Protein Atlas): Mitochondria; Nucleoplasm
Gene Ontology:
Biological process: axonal transport of mitochondrion
Cellular component: mitochondrion; mitochondrial outer membrane; axon cytoplasm
Homologues: Orthologues: chimpanzee ARMCX2 (99% identical), macaque ARMCX2 (98% identical), pig ARMCX2 (85% identical), rabbit ARMCX2 (82% identical), dog ARMCX2 (82% identical), guinea pig ARMCX2 (79% identical), mouse Armcx2 (79% identical), rat Armcx2 (78% identical), zebrafish armc10 (16% identical), tropical clawed frog armc10 (16% identical), Caenorhabditis elegans Y67A10A.7 (9% identical). Paralogues in human: ARMCX4 (31% identical), ARMCX1 (30% identical), ARMCX3 (24% identical), ARMC10 (24% identical), GPRASP1 (17% identical), GPRASP2 (16% identical), ARMCX6 (16% identical), ARMCX5 (14% identical), GPRASP3 (10% identical), ARMC12 (10% identical).
Diseases named in the same sentence as ARMCX2 in open-access papers:
ARMCX2 is named in the same sentence as 8 diseases in open-access papers, as found by Europe PMC text mining. Sharing a sentence is not in itself a finding about the gene and the disease. The quoted sentences say what the papers report.
colorectal cancer (1 paper, 2022). A primary or metastatic malignant neoplasm that affects the colon or rectum. "Among them, MMP12 was highly expressed in colorectal cancer tissues, while ARMCX2, CEBPA, CXCL13, FABP4, HOXC6, SIGLEC1 and VSIG4 were more expressed in normal tissues than in cancer tissues." (PMID 36544770, 2022).
gastric cancer (1 paper, 2020). A primary or metastatic malignant neoplasm involving the stomach. "On the basis of GSEA results, we deduced that both ARMCX1 and ARMCX2 were involved in the pathway and biological processes that are associated with the progress and treatment of gastric cancer and may serve as a GC prognostic marker." (PMID 32685472, 2020). "More importantly, ARMCX1 and ARMCX2 are more highly expressed in adjacent normal tissues than in tumor tissues, leading to better OS in patients with gastric cancer, although the mechanism of action needs further clarification." (PMID 32685472, 2020).
gastric tumors (1 paper, 2020). "ARMCX1, ARMCX2, and ARMCX4 were lowly expressed in primary gastric tumors and has a high expression in normal gastric tissues." (PMID 32685472, 2020).
liver cancer (1 paper, 2022). An epithelial or non-epithelial malignant neoplasm that arises from the liver. "Indeed, two of the examples we have highlighted, ARMCX2 and MAGEH1, have previously demonstrated promoter hypermethylation and gene silencing in ovarian and liver cancer, respectively." (PMID 35654826, 2022).
cancer (2 papers, 2022). A tumor composed of atypical neoplastic, often pleomorphic cells that invade other tissues. "Two examples of CpG probes resistant to drug induced demethylation in the HCT116 parental cells (ARMCX2 and MAGEH1), showed the behavior expected for X-linked genes in non-cancer tissues." (PMID 35654826, 2022). "Unfortunately, little is known about the functional roles of ARMCX2 and MAGEH1 aside from their expression patterns in non-cancer human tissues." (PMID 35654826, 2022).
tumor (2 papers, 2011 to 2020). "Nomogram risk scoring includes age, tumor stage, and the expression level of ARMCX1 and ARMCX2 to calculate 1-year, 5-year, and 10-year related survival rates." (PMID 32685472, 2020). "The higher total points, the lower survival rate, and the results substantiated that high expression levels of ARMCX1 and ARMCX2, age of the patient (>60 years old), and advanced tumor stage established a prognostic feature that conduced to the highest risk for poor OS." (PMID 32685472, 2020). "ARMCX2 encodes a member of the ALEX family of proteins and may play a role in tumour suppression." (PMID 21740549, 2011).
ARMCX2 also shares sentences with these, for which no sentence is quoted: anaphylaxis (1 paper); ovarian carcinoma (1).